LINC00910 (long independently transcribed non-coding RNA 910)
Gene: Long non-coding RNA gene on chromosome 17 (43,338,741 to 43,389,226, reverse strand). Ensembl gene ENSG00000188825.
Gene Ontology:
Molecular function: pre-mRNA branch point binding
Biological process: mRNA branch site recognition
Cellular component: U2 snRNP
Diseases named in the same sentence as LINC00910 in open-access papers:
LINC00910 is named in the same sentence as 8 diseases in open-access papers, as found by Europe PMC text mining. Sharing a sentence is not in itself a finding about the gene and the disease. The quoted sentences say what the papers report.
breast carcinoma (2 papers, 2019 to 2021). "PITPNC1 is a reported oncogene in breast cancer, and LINC00910 is a putative oncogenic noncoding RNA." (PMID 34439480, 2021). "To test whether a decrease in enhancer activating H3K36me3 mark impacts gene transcription, we first assessed gene expression of PITPNC1 and LINC00910 following 9-day treatment of MCF10CA1a breast cancer cells with 7 μM PTS." (PMID 34439480, 2021). "In the presented study, we constructed and validated a 10‐lncRNA‐based signature (HAGLR, MIR210HG, RGMB‐AS1, TMEM161B‐AS1, CADM3‐AS1, LINC00293, LINC00910, LINC01187, PDZRN3‐AS1 and ZBED5‐AS1) to predict RFS for patients with breast cancer." (PMID 31429520, 2019). "Indeed, OCT1 depletion in MCF10CA1a breast cancer cells led to a profound downregulation of PITPNC1 and LINC00910 and exerted anti-cancer effects." (PMID 34439480, 2021).
leukemia (1 paper, 2019). A malignant (clonal) hematologic disorder, involving hematopoietic stem cells and characterized by the presence of primitive or atypical myeloid or lymphoid cells in the bone marrow and the blood. "This component is particularly interesting because it contains several lncRNAs with very high degree/betweenness, so potential core players in the leukemia regulatory network, but of unknown function, such as LINC00854 and LINC00910." (PMID 31142264, 2019).
cancer (3 papers, 2019 to 2024). A tumor composed of atypical neoplastic, often pleomorphic cells that invade other tissues. "Many of the other lncRNAs, such as LINC01220, CYTOR, LINC00910, LINC00511, PURPL, and MZF1-AS1, have been described in association with different types of cancer, mainly with proliferation and migration of the tumour cells." (PMID 38616192, 2024). "Others, such as LINC01220, CYTOR, LINC00910, LINC00511, PURPL, and MZF1-AS1, have been described so far only in cancer." (PMID 38616192, 2024). "We hypothesize that several lncRNAs like LINC00909, LINC00910, and LINC00263 are likely to titrate RBPs in cancer, resulting in the functional disruption of RBPs and their downstream functions." (PMID 31390792, 2019).
LINC00910 also shares sentences with these, for which no sentence is quoted: cardiovascular disorder (1 paper); hepatocellular carcinoma (1); lung carcinoma (1); thyroid papillary cancer (1); tumour (1).